CD69 (CD69 molecule)
Diseases named in the same sentence as CD69 in open-access papers (continued):
Sharing a sentence is not in itself a finding about the gene and the disease.
tumor (continued). "Therefore, we determined CD69 and CTLA-4 levels at different time points after in vitro incubation of T cells isolated from mouse spleens together with DCs and tumor cells (B78-D14 or B16-EpCAM) in the presence of Surek or BiLu." (PMID 27966460, 2017). "PBMC co-cultured with or without BiTE in the presence of tumor cells were also assessed for the activation markers CD69 and CD25." (PMID 28938530, 2017). "Strikingly, CD69+ Tregs, recovered from tumor draining and non-draining lymph nodes, were more suppressive of Tconv proliferation than their CD69− counterparts." (PMID 26433463, 2015). "Tumor-infiltrating leukocytes (TIL) were isolated from the tumors on d21 after treatment, and we observed increased proportions of activated NK cells that express early activation marker CD69 in co-treated animals." (PMID 26287667, 2015). "Furthermore, we confirmed that the expression of CD4 and CD8 as well as Foxp3, FR4, CD69, CD154, and CD25 was markedly decreased in the tumor tissues from the tumor-bearing BALB/c nude mice." (PMID 25365349, 2014). "In line with this notion, our results clearly show that the combination of 2-DG and radiation elicits anti-tumor immune response by not only restoring the levels of CD4+ cells, but also the levels of molecules related to its signaling i.e. CD44, CD69, CD45, TCR-β, TCR-γδ and CD28." (PMID 25248151, 2014). "With regard to the expression of the earlier activation marker CD69, we found an increase in the percentage of CD69+CD4+ T cells in the spleen following the combined treatment, and a tendency to a reduction of the cell percentage in the tumor." (PMID 24608924, 2014). "We observed a similar increase in the frequency of CD69+ T cells following co-incubated with TSA-treated or irradiated tumor cells (data not shown)." (PMID 24829753, 2013). "We have also observed increased expression of CD25 and CD69 on T cells following co-incubation with irradiated tumor cells compared to non-irradiated tumor cells." (PMID 24829753, 2013). "The absence of CD69 from the tumour cells suggests that they were derived from T cells at a stage prior to positive selection." (PMID 22558084, 2012). "However, we observed a small but significant increase in CD69 expression in activated CD4+ T cells, when cells were stimulated in vitro after in vivo tumor challenge." (PMID 23144743, 2012). "However, the number of T lymphocytes expressing the activation markers CD69 (very early activation antigen,) and CD25 (IL-2 receptor α chain,) was in general higher in tumor-burdened animals compared to tumor-free LLA-TG-3 mice." (PMID 22674057, 2012). "CD69 is upregulated upon activation by cytokines, TLR agonists or tumor cells." (PMID 23098236, 2012). "Whether the mice had received resting or reactivated memory cells, the OT-I cells recovered from the tumor showed an activated T cell phenotype with low CD62L expression and high levels of CD69 and 4-1BB." (PMID 20543982, 2010). "Furthermore, cilengitide, WP1066, or AR-A014418 treatment increased activated CD4+ (CD45+CD3+CD8–CD4+CD69+) and CD8+ T cells (CD45+CD3+CD8+CD4–CD69+), and these effects were improved when CT2A tumor–bearing mice received the treatment with cilengitide combined with WP1066 or AR-A014418." (PMID 40131864, 2025). "However, neither the IL‐2 and IFNγ levels nor the surface expression of CD69 of T cells activated by I3A‐treated tumor cells was changed by autophagy inhibitors." (PMID 40583248, 2025). "When combined with activated CTLs, it upregulated CD25 and CD69 expression on effector cells, increased the secretion of IL-2, tumor necrosis factor-α (TNF-α), and IFN-γ in vitro, and significantly curbed subcutaneous tumor growth and extended the survival time of tumor-bearing mice in vivo." (PMID 41164200, 2025).
tumor (continued). "Another study found that CD69 could serve as a prognostic marker for SKCM, influencing immune response through interactions with genes like PTPRC and IL7R, and impacting tumor progression by regulating the tumor immune microenvironment." (PMID 40547036, 2025). "Another study of NK cells in lung cancer demonstrated that the majority of tumor-infiltrating NKs lacked CD16 expression, and observed that the CD69 + tissue-resident NK cells (trNK) subset was enriched in the tumor center vs. distal lung in both adenocarcinoma and squamous lung histologies." (PMID 40849493, 2025). "Concurrently, an analysis predicated on two markers of T-cell activation, CD69 and CD25, revealed a substantial augmentation in the proportion of activated CD8 T cells within the tumor, along with a notable escalation in the concentration of cytokines in the interstitial fluid of the tumor." (PMID 40598593, 2025). "This study could serve as the foundation of a broadly applicable and clinically useful way to promote the generation of vaccine specific Trm and provides direct evidence that intratumoral CD8+CD69+CD103+ and CD8+CD69+CD49a+ cells are indeed Trm and that Trm contribute to tumor immunity." (PMID 40162209, 2025). "In the tumor microenvironment, administration of PD‐L1 nb plasmids reduced PD‐1 expression on CD8+ T cells and mitigated T cell exhaustion, while co‐administration with GM‐CSF‐peptides significantly increased memory CD8+ T cells and activated CD8+ T cells (CD8+CD69+)." (PMID 40245119, 2025). "Using isolated tumor tissue, we analyzed gene expression related to cytotoxicity (Perforin, Granzyme B, Granulysin, and FasL), inflammatory or chemotactic cytokines (IFN-γ, CXCL9, CXCL10, and CXCL11), and CD8+ T cell activation and proliferation (CD69, Tbx21, IL-2, and IL-12b)." (PMID 39066478, 2024). "Flow cytometry measurements revealed that the proportions of CD25+ or CD69+ activated CD8+ T cells and CD107a+ cytotoxic subgroups were upregulated (P = 0.0130; P = 0.0627; P = 0.0260), corroborating the improvement of T cell-based adaptive anti-tumor immunity." (PMID 38600469, 2024). "We observed a significant increase in the number of CD69− and CD69+CD103−/+ populations within both polyclonal CD8+ and SIINFEKL+ TIL, suggesting that CD47 × PD‐L1 BisAb treatment promotes a wide‐spread influx of T cells including both tumor‐reactive and polyclonal T cell populations." (PMID 39584189, 2024). "Notably, CD69 expression, an activation marker for CD8+ T lymphocytes, significantly increased in the combination treatment group in contrast to the PBS group, PLX3397 group, and RT group within the Lewis subcutaneous transplant tumor model." (PMID 39165639, 2024). "However, in co-cultures where PAI-1 was added to tumor cells, no concomitant elevation in CD69 expression was observed." (PMID 38779680, 2024). "As anticipated, upon encountering tumor antigens, the tumor-specific CTLs in conjunction with LPS-RGD-Nb36-DOX were able to quickly blockade the CTLA-4/B7 axis, as seen by increased expression of CD25, CD69, and CD62L as well as increased cytokine secretion (TNF-α, IFN-γ, and IL-2)." (PMID 38824143, 2024). "The release of CD69 and CD107a in the armored-T cells was significantly increased, when compared with the CON-T cells, indicating that the activation potential of armored-T cells was higher when stimulated with tumor cells and antibody than that of CON-T cells." (PMID 38953027, 2024). "Moreover, a minor to medium increase of GZMB expression and upregulation of activation of CD69, IFN-γ, CD25 and CD107 were detected in tumor-infiltrating CD8+ T cells from the B16F10 tumor graft after silencing Mi-2β, which was strongly augmented by anti-PD-1 treatment." (PMID 38461299, 2024). "Interestingly, the [CD20×NKG2D#24] bibody with low NK cell activation capacity in terms of CD69 induction was not able to increase tumor cell lysis in combination with monoclonal antibodies." (PMID 37965326, 2023).
tumor (continued). "R848@M2pep-MPsAFP treatment also significantly increased the numbers of the activated CD8+CD69+ T cells, CD8+IFNγ+ T cells and CD8+GzmB+ T cells in spleens of orthotopic Hepa1-6 tumor-bearing mice, suggesting that R848@M2pep-MPsAFP efficiently activated the systemic antitumor immunity." (PMID 37704614, 2023). "A PKCβ involvement in the increase in CD69 levels was involved in tissue residency was also suggested, along with the production of CXCL8 chemokine, the latter reported as pro-tumorigenic in the TME by supporting tumor persistence, EMT, angiogenesis and impairment of anti-tumor responses." (PMID 37626933, 2023). "In addition, the tumour-infiltrating CD8+CD69+ expressing cells were negative for CD49b markers, suggesting these were not NK cells but rather activated lymphocytes." (PMID 37887559, 2023). "Moreover, the frequencies of CD69+ T cells were significantly higher in the circulating peripheral blood and infiltrating tumour tissue post-CROSS CRT but not post-FLOT in OGJ patients." (PMID 35986757, 2023). "Notably, we observed an increased presence of CD69+CD8+ T cells within the tumor sites, indicating enhanced infiltration of effector T cells (or tumor-infiltrating lymphocytes, TILs) into the tumor microenvironment." (PMID 37673917, 2023). "The proportion of DN T cells co-expressing CD44 and CD69 (“DN TRM-like”) in captopril-treated regenerating liver tissue significantly increased, and this corresponded with an increase in PD-1 expression on DN TRM-like cells in captopril-treated regenerating liver and tumour." (PMID 35563674, 2022). "We investigated whether the T-cell populations observed in regenerating liver and tumour tissue had features of TRM, defined by the expression of murine hepatic TRM markers, CD44 and CD69 (termed “TRM-like cells”), and assessed the effect of captopril on these populations and their PD-1 expression." (PMID 35563674, 2022). "T cells infiltrating KPAR tumours were alsomore activated, with a higher proportion of effector memory CD8+ andCD4+ T cells andincreased expression of the activation marker CD44 on both CD8+ andCD4+ T cells as well as the early activation marker CD69 onCD8+ T cells." (PMID 35930804, 2022). "Also, MNK inhibitors did not affect the expression of PD-1, Prf1, or CD69 in CD8+ T cells isolated from the spleens of non–tumor-bearing mice and treated with MNK inhibitors ex vivo." (PMID 35380995, 2022). "Similarly to what was observed within the tumors, an increase in CD69+ CD8+ T cells was not seen in the lymph nodes from B16F10 tumor-bearing animals." (PMID 36923556, 2022). "Therefore, the higher expression level of CD69 and CD25 could be assumed to be a direct result of a tighter T cell: tumor cell aggregation induced and maintained by the TbsAb.short molecule." (PMID 36291540, 2022). "As a result, treatment with tumor exosomes was observed does not alter CD69 expression." (PMID 35031075, 2022). "Interestingly, upregulation of CD25 and CD69 in the AB928 containing condition was more pronounced than in the vehicle control condition when CAR T cells were activated by antigen-expressing tumour cells, but not when activated with recombinant protein." (PMID 36266575, 2022). "Flow cytometry data demonstrated the pronounced increase in the percentage of CD69+ cells in both CD4+ Th (p < 0.002) and CD8+ T-cells (p < 0.002) and moderate increase in the percentage of CD25+ among CD4+ Th cells (p < 0.03) in all tumor-bearing mice in comparison with “Control” group." (PMID 36555468, 2022). "A large subset of tumor-infiltrating CD8+ T lymphocytes is represented by tissue resident (Tres) memory CD8+ T cells, that accumulate in different human cancers and are characterized by the expression of CD103 integrin and C-type lectin CD69, which both contribute to their residency features." (PMID 36428727, 2022).
tumor (continued). "Therefore, it is tempting to speculate that the increased expression of CD69 and PD-1 on both CD4 effectors and CD8 T cells resulted from yet undefined soluble factors released by tumor cells." (PMID 36458012, 2022). "The SKW-3 cells expressing the positively-selected TCRs induced a significant increase in the expression of CD69 on co-culture with autologous but not allogeneic tumor organoids, highlighting the presence of patient-specific antigens that are recognized by the TCRs selected in opT cell populations." (PMID 34789550, 2021). "However, IL-6 neutralization moderately enhanced the ratios of CD8+ T cells in tumor-associated CD45+CD3+ T cells, but did not activate these T cells, as indicated by no increases detected in Ki67+, IFN-γ+, or CD69+ activating T cells in CD45+CD3+ T cells." (PMID 34103524, 2021). "Moreover, CD69 controls T-cell differentiation through its interaction with galectin-148, and TGF-β-triggered CXCL12/CXCR4 signaling has been demonstrated to promote tumor invasion, metastasis, and therapeutic resistance." (PMID 34001881, 2021). "Furthermore, we performed flow cytometric experiments to detect some parameters (NK1-1, CD107a, CD69, tumor necrosis factor (TNF)-α, and interferon (IFN)-γ) on NK cells in tumors to investigated the state about tumor-infiltrating NK (TINK) activation, with the fresh tumor tissue from mouse." (PMID 34471091, 2021). "Moxibustion upregulated the infiltration of CD4+ T cells and Th1 cells in the tumor, and the combinatorial therapy increased the proportion of CD8+ cytotoxic T cells (CTLs), CD4+T cells, Th1, Th9 cells, and M1 macrophages, as well as the expression of Cd69, Ifng, and Cd86 mRNA." (PMID 33456484, 2020). "Besides tumor stage-dependent induction of apoptosis by CD45(−) exosomes, they were also responsible for suppression of CD8+ T cell activation as reflected by a high suppression of CD69 on activated CD8+ T cells." (PMID 32708274, 2020). "Tumor infiltrating T cells in regressors were metabolically fitter than those in non-regressors, with significant enrichments of antigen-specific CD8+ T cells, T cell factor 1 (TCF1)+ T cells and CD69− T cells, compatible with induction of a sustained tumor-specific T cell response." (PMID 33093155, 2020). "We propose that a panel comprising the markers CD45RA, CCR7, CD95, CD69, CD57, PD-1 as well as CD28, CD40L, and ICOS should be validated in larger cohorts of patients and used to develop a model aiding in the identification of NSCLC patients prone to show tumor regression upon anti-PD-1 therapy." (PMID 31176366, 2019). "Instead, it could reflect increased retention due to higher CD69 expression and possibly increased frequency of central memory CD44+ CD27+ T cells at the tumor site which are known to be more efficacious in mouse models of ACT, as found in the disseminated tumor model." (PMID 31249570, 2019). "Most interestingly, CD49a was frequently co‐expressed with CD69 and CD103, and in vivo blockade of CD49a or CD103 in a C57BL/6 melanoma mouse model significantly impaired control of subcutaneous B16‐OVA tumors, supporting the notion of TRM cell‐mediated anti‐tumor immunity." (PMID 31230406, 2019). "Taking into account three immunological readouts after chemotherapy: CD3 internalization and CD69 expression in T cells and the IL-12 production in DCs, became evident that the explanatory values of CD69 and IL12 are useful for predicting tumor response to chemotherapy." (PMID 29334915, 2018). "To address this, following tumor inoculation we measured global cytokine mRNA differences, including TGFβ, TNFα, IL-10 and IFNγ, between WTTU and L3TU groups on day 5, the time point where we observed the greatest differences in cellular accumulation and CD69 positivity." (PMID 29109732, 2017).
tumor (continued). "We also examined the numbers of CD8+ T cells and CD69+ activated immune cells in this validation TNBC cohort, and strong positive correlations were found between the numbers of CD8+ or CD69+ cells and the HLA-ABC expression in tumor cells as well as the TIL levels assessed on the H&E stained slides." (PMID 27121061, 2016). "Patients with high percentages of CD94+/CD69+ NK cells have low Hsp70 serum levels and also a lower GTV, which indicates that these NK cells might be able to control the growth of mHsp70-positive tumor cells." (PMID 26579130, 2015). "In this regard, statistical comparison between the no tumor, low and high tumor burden group revealed significant differences for CD69+ CD4+ lymphocytes in spleens and for both CD25+ CD8+ and CD69+/CD25+ CD4+ lymphocytes in ndLN (all p < 0.05; Kruskal–Wallis test)." (PMID 22674057, 2012). "However TCR transgenic SH2D2A-deficient peripheral CD4+ T cells in tumor mice displayed higher CD69 surface expression compared to mice without tumor (p = 0.05) or unchallenged mice (p<0,007)." (PMID 23144743, 2012). "Parental Jurkat cells or anti-NIP CIR-expressing Jurkat cells (JurkatαNIP-CIR) could not be activated to express CD69 with any of the tumor cell lines tested." (PMID 19777065, 2009). "Moreover, in the tumor microenvironment, a proportion of CD69+CD103+ T cells may reflect exhausted T cells rather than genuine TRM, making it difficult to distinguish TRM identity based solely on surface markers." (PMID 41361844, 2025). "Furthermore, CD69+ TRM cells can become exhausted in a highly immunosuppressive TME; however, their presence in non-tumor areas may allow them to function under less suppressive conditions, effectively serving as a frontline defense against microscopic residual disease occurring after resection." (PMID 40361474, 2025). "Following co-culture with different tumor targets, we noted that Siglec-7-based CSR could trigger an upregulation of these markers compared to TCR-only control; for example, S7-41BB leads to 43% more expression CD69, 20% more 4-1BB, and 12% more CD25 expression in cocultures with 888/A2." (PMID 40433387, 2025). "WiDr tumor cells have a higher cell surface expression of BTN3A1 compared to the WM9 and HAP1 cell lines, which could explain the higher killing percentage and significant increase of CD25 and CD69 on the challenged Vδ2 T cells because BTNs are well described stimulants of the Vδ2 TCR." (PMID 38426099, 2024). "Furthermore, there were significantly higher frequencies of PD-1+ and CD69+ NK cells in the tumour (n = 8–10) of OAC patients relative to the circulation (n = 17–20); PD-1: blood versus tumour (20.03% vs. 38.16%, p = 0.011), CD69: blood versus tumour (13.14% vs. 60.18, p < 0.0001)." (PMID 38369570, 2024). "To further understand the molecular mechanism by which the FGL2-blocking scFv induces CD69+CD8+ TM cell generation, we analyzed CyTOF data for chemokine receptors (i.e., CCR2, CXCR3, CXCR2, and CX3CR1) that may affect T cell infiltration and recruitment to tumor sites." (PMID 36759517, 2023). "Besides upregulation of the early activation marker CD69, we report decreased levels of DNAM-1 and increased NKG2A expression on NK cells in coculture with MV-infected tumor cells, which is most pronounced in combination treatments with either tumor-specific MV-BiKE, or MV plus BiKE." (PMID 36765035, 2023). "However, tumor CD69+CD103+ TRM-like cells were not correlated with tumor size." (PMID 36229613, 2022). "FcεRIγ− adaptive CD56dim NK cells, isolated from liver tissue irrespective of non-tumor or tumor origin, displayed a low expression of these tissue-resident markers, whereas CD56bright NK cells obtained from liver tissue expressed higher levels of CD69, CXCR6 and CD49a." (PMID 34199483, 2021).